CSF1 (colony stimulating factor 1)
Diseases named in the same sentence as CSF1 in open-access papers (continued):
Sharing a sentence is not in itself a finding about the gene and the disease.
tumor (continued). "This increase, however, is paralleled by an expansion of immunosuppressive immune cells such as Tregs and TAMs through an increase in expression of cytokines by tumor cells, including CSF-1." (PMID 28714919, 2017). "Cytotoxic therapies can induce tumour cell expression of CSF-1, which results in an increased macrophage infiltration." (PMID 28210073, 2017). "Macrophage accumulation within and movement through a tumor is often stimulated by tumor cell production of the mononuclear phagocytic growth factor, colony-stimulating factor-1 (CSF-1)." (PMID 28629162, 2017). "TAMs originate from circulating monocytes, which are recruited to the tumor microenvironment and reprogrammed by tumor-derived factors such as S1P, colony-stimulating factor-1, VEGF-A, and CC chemokine ligand 2 (CCL2)." (PMID 28804221, 2017). "ADT can induce infiltration of TAMs into the TME through the increased tumor expression of cytokines such as CSF-1 and CCL2." (PMID 28714919, 2017). "The expression of CSF1 in a broad array of human and murine tumor cell lines was increased after irradiation in vitro as well as in vivo in implanted tumors." (PMID 28348554, 2017). "Another newly discovered cytokine IL-34 expressed by osteosarcoma cells sharing CSF-1R with CSF-1 recruited M2 macrophages, and its overexpression increased tumor growth, vascularization, and metastasis." (PMID 28197019, 2017). "EGF is well-known for its ability to enhance the invasion of tumor cells, while CSF1/2 are able to recruit stromal cells, such as macrophages, to the tumor cells." (PMID 28008153, 2017). "On the contrary, overexpression of this CSF-1 protein increased the rate of tumour progression and metastasis." (PMID 29065107, 2017). "Taken together, these findings demonstrate that myeloid cell-derived autophagy promotes the survival and infiltration of macrophages, which further differentiate into M2-like immunosuppressive cells via tumor-derived CSF-1." (PMID 28686632, 2017). "Preclinical models have linked the inhibition of CSF1/CSF1R signaling to the reprogramming of the monocytoid population, shifting the population from tumor promoting monocytes (MDSCs) to that of tumor suppressive, antigen presenting macrophages." (PMID 28492495, 2017). "Consistently, the short-term blockade of CSF1R after micrometastasis formation showed negligible effects on the metastatic tumor expansion, although long-term genetic MAM depletion through loss of Csf1 substantially inhibits metastasis." (PMID 29387063, 2017). "TAMS can be recruited into the primary tumor by cancer cell derived chemokines and cytokines (e.g. CSF1, VEGFA, CXCL2, CXCL12)." (PMID 29037250, 2017). "Blocking CSF-1 expression in a xenograft model significantly decreased the growth capacity of tumor cells." (PMID 28170411, 2017). "Tumor microenvironment-derived CSF-1 is the mast regulator of recruitment and differentiation of circulating monocytes, and knockout of CSF-1R showed depletion of TAMs." (PMID 28694739, 2017). "In tumor tissues, CSF-1 or IL-10 produced in tumor cells induce the differentiation of TAMs to M2 macrophages." (PMID 29286292, 2017). "The recruitment and accumulation of TAMs into tumors are initiated by macrophage chemoattractants [e.g., CCL2/monocyte chemoattractant protein 1 (MCP-1), colony-stimulating factor 1 (CSF-1)] and it is well established that TAMs drive tumor progression." (PMID 28769933, 2017). "Our present study provides new information that miR-1207-5p can target CSF1, an essential growth factor for macrophage, and thus modulate the tumor microenvironment." (PMID 27107415, 2016). "Since PI3K p110δ is a critical mediator of CSF-1-induced macrophage motility, signaling downstream of the CSF-1R is therefore integral to the promotion of tumor cell invasion by BMM." (PMID 31453214, 2016). "Tumor cells secrete CSF-1 that promotes TAM production of EGF, and TAM-derived EGF stimulates tumor cell CSF-1 secretion." (PMID 26980947, 2016).
tumor (continued). "Colony-stimulating factor 1 is secreted by tumor cells, which in response increases macrophages activity within the tumor microenvironment." (PMID 27051190, 2016). "First, the tumor cells secrete soluble mediators, such as M-CSF/CSF-1, VEGF, and TGFβ, which recruit macrophages to the tumor and maintain their viability, while polarizing them towards M2-activation." (PMID 26997761, 2016). "Using genetic approaches, seminal studies demonstrated that CSF-1 is critical for macrophage recruitment and differentiation in tumor microenvironment of MMTV-PyMT mice." (PMID 26884646, 2016). "This suggests the anti-CSF1 antibody treatment in vivo reduced tumor macrophage recruitment and specifically blocked type 2 macrophage recruitment into the tumor and thus delaying tumor growth and skin invasion, hallmarks of IBC." (PMID 27756885, 2016). "For example, overexpression of macrophage colony-stimulating factor 1 (CSF1 or M-CSF) leads to accelerated tumor progression in mice and human." (PMID 27692066, 2016). "CSF1 of the cancer cells can increase the migration ability of macrophages through autocrine loop, thus promotes the tumor invasion and metastasis, and further stimulates the secretion of CSF1." (PMID 27107415, 2016). "While a number of tumor-derived factors have been implicated in the recruitment and survival of LAM, colony-stimulating factor-1 (CSF-1, or M-CSF) is required for normal macrophage homeostasis and viability." (PMID 28031823, 2016). "The human NSCLC data supported the concept that miR-1207-5p has anti-metastasis or tumor suppressor functions, whereas CSF1 has pro-metastasis or oncogene function." (PMID 27107415, 2016). "The time to reach tumor resection in the anti-CSF1 was slower than tumors in the IgG group (105.7 days vs. 209.3 days, P < 0.001)." (PMID 27756885, 2016). "Macrophage plays vital role in the tumor microenvironment, and CSF1 is essential for proliferation, differentiation, and function of macrophage." (PMID 27107415, 2016). "CSF-1 expression was positively correlated with Fuhrman grade (P = 0.001 in the training cohort and P = 0.007 in the validation cohort) and tumor necrosis (P = 0.013 in the training cohort and P = 0.039 in the validation cohort)." (PMID 25886010, 2015). "This is in accordance with previous reports describing CSF1 (ligand) expression in tumour cells but the receptor, CSF1R, in the surrounding TAM populations." (PMID 26066800, 2015). "IL-4 induces “alternative” activation of M2-like macrophages; and in response to other cytokines, including TGFβ, IL-10, and CSF-1, this macrophage type has been reported to acquire properties that enhance tumor cell growth, invasion and metastasis." (PMID 27563494, 2015). "CSF-1 is secreted by various types of cells like monocytes, fibroblasts, endothelial cells, and tumor cells." (PMID 25886010, 2015). "Previous studies have detected anti-tumour activity after disrupting the CSF1/CSF1R signalling pathway, probably as a result of blocking the recruitment and inhibiting the activation of TAMs." (PMID 26066800, 2015). "The tumour microenvironment is highly complex and we have shown dual roles for the cytokine, CSF-1 and CCL2 in the context of macrophage activation, suggesting a spectrum of macrophage activation states." (PMID 26174804, 2015). "TAMs gather in the tumour microenvironment in response to cytokines such as Csf1, a STAT1 target gene." (PMID 25915429, 2015). "Meanwhile, overexpression of CSF1 receptor (CSF1R) positive cells has been observed in tumorous tissues and high expression levels of CSF1 mRNA in PVNS." (PMID 25854167, 2015). "TAMs have an M2 phenotype and are predominately activated by IL-4, IL-10 and CSF-1 secreted by the tumour, whereas M1 macrophages are classically activated by lipopolysaccharide (LPS) and IFNγ and driven to phagocytosis." (PMID 26174804, 2015).
tumor (continued). "CSF-1 has been demonstrated as a mediator polarizing macrophages into an M2 phenotype which can promote tumor-induced immunosuppression in established tumors." (PMID 25886010, 2015). "Many studies have demonstrated that CSF-1 can polarize macrophages in the tumor microenvironment to an M2 phenotype, which has anti-inflammatory function, favors angiogenesis, and promotes tumor growth." (PMID 25886010, 2015). "Tumor cell migration toward TMEM in vivo occurs in association with macrophages and involves epidermal growth factor (EGF)/colony stimulating factor 1 (CSF-1) paracrine signaling." (PMID 26112005, 2015). "High expression levels of the macrophage colony-stimulating factor 1 (CSF1) are another indicator of tumor progression and poor survival in HCC patients." (PMID 26020769, 2015). "Tumor-derived factors like IL10, IL6, CSF1, and VEGF interfere with DC maturation, causing failure to migrate to the tumor-draining lymphoid organs, and to provide the appropriate co-stimulatory signals required to stimulate T cells." (PMID 26500653, 2015). "In RCC, apart from polarizing macrophages into an M2 phenotype, CSF-1 could also lead to the activation of signal transducer and activator of transcription-3 (Stat3) which promotes cell survival and proliferation as well as immune responses associated with tumor progression." (PMID 25886010, 2015). "While hypoxic microenvironment downregulates CSF-1 expression in several tumors cell lines, the normoxic tumor cells express much upregulated levels of CSF-1." (PMID 25051364, 2014). "Insertions in both Csf1 and Fli1 were cloned from sections of fresh frozen tumor found in this mouse." (PMID 25423036, 2014). "In CSF-1-null mice, macrophage infiltration of the tumor site was significantly lower and accompanied by impaired development of the vasculature network." (PMID 24634660, 2014). "In the present study we performed RNA-sequencing of three TSGCT in an attempt to elicit more information on the mechanisms of altered CSF1 expression in this tumor type." (PMID 24604026, 2014). "The importance of CSF1 to tumor development and to the stromal cells has been recognized recently in various experimental systems." (PMID 25313137, 2014). "CSF1-silenced H358 cells resulted in significantly smaller tumors, showing increased fibrosis and a decrease in tumor infiltrating macrophages." (PMID 25313137, 2014). "TAM originate from circulating monocytes which are recruited to the tumor site and programmed by tumor-derived factors such as colony-stimulating factor-1 (CSF-1), vascular endothelial growth factor A (VEGF-A) and CC chemokine ligand 2 (CCL2)." (PMID 24634660, 2014). "Xenograft experiments have further demonstrated that tumor cells transfected with CSF-1 gene exhibited an increase in TAM infiltration." (PMID 25125485, 2014). "Alternatively, VEGF-A expression can be induced by tumor-released CSF-1 (M-CSF), which acts through NF-κ B activation and, in combination with CCL2, promotes pro-angiogenic functions of macrophages." (PMID 24634660, 2014). "Mechanistically, tumor cells synthesize CSF-1 in order to promote macrophage migration and macrophage-derived epidermal growth factor (EGF) enhances tumor cell invasion." (PMID 25125485, 2014). "This switching from hypoxic to normoxic conditions and further mantainence for 24 hrs was likely to upregulate CSF-1 levels as normoxic tumor cells are known to express much higher levels of CSF-1 than the hypoxic tumor cells." (PMID 25051364, 2014). "Important populations in all these pro-tumor processes are M2 macrophages, N2 neutrophils, regulatory T cells, and myeloid derived suppressor cells; the main effectors molecules are CSF-1, IL-6, metalloproteases, VEGF, PGE-2, TGF-β, and IL-10." (PMID 23577028, 2013). "Treatment of tumor cells with EGCG resulted in a significant decrease of both CSF-1 and CCL-2 expression." (PMID 24044575, 2013).
tumor (continued). "It is known that tumor cells secrete CSF-1, a chemotactic factor that actively recruits monocytes to the tumor site." (PMID 23762835, 2013). "Colony stimulating factor-1 (CSF1) is a protein that increase tumor angiogenesis and promotes metastatic potential in beast cancer." (PMID 23593148, 2013). "Tumor cells produce colony-stimulating factor-1 (CSF-1) and Chemokine (C-C motif) ligand 2 (CCL2), which are two major attractants and growth factors for TAM." (PMID 24044575, 2013). "Both cell-surface and secreted CSF-1 produced by tumor cells metastatic to bone can contribute to induce osteoclast formation." (PMID 24019914, 2013). "This was not simply due to an insufficient exposure to TINs since chronic depletion of TAMs in PTCs of Csf-1 knockout mice also impaired the tumor phenotype." (PMID 23372702, 2013). "While the regulation and function of IL-34 during cancer progression remain to be investigated, experimental and clinical evidence have largely documented the central role of CSF-1 in tumor development and metastasis." (PMID 24019914, 2013). "CSF-1 recruits peripheral macrophages to the tumor site via CSF-1 receptor (CSF-1R) and is vital to induction of M2 phenotype." (PMID 24202450, 2013). "Activation of CSF-1R by its ligand is likely to occur in an autocrine manner in tumor cells in which CSF-1R and CSF-1 are co-expressed, or in paracrine manner, when CSF-1R is stimulated by CSF-1 released by fibroblasts." (PMID 23561040, 2013). "In agreement, knockout mice for the primary tumor macrophage chemoattractant, CSF-1, have a slow tumor growth, low progression to invasive stages, and reduced metastasis." (PMID 23577028, 2013). "Other chemoattractants that have been shown to stimulate microglia/macrophage migration into the tumor include colony stimulating factor-1 (CSF-1), macrophage colony-stimulating factor (M-CSF), and glial-derived neurotrophic factor (GDNF)." (PMID 23983766, 2013). "Xu and colleagues demonstrated that tumor irradiation of C57BL/6 mice implanted with syngeneic RM-1 prostate cancer cells led to an increase in CSF1 expression by the tumor cells, which was dependent on activation of ABL-1 tyrosine kinase." (PMID 24829747, 2013). "In humans, CSF1 levels have been shown to correlate with macrophage, tumor density, and poor prognosis." (PMID 23577028, 2013). "In order to imitate the tumor microenvironment, we introduced the chemotactic factor CSF-1 into our experimental protocol." (PMID 24116086, 2013). "Radiation-induced recruitment of TAMs appears to occur in a similar manner as that caused by tumor hypoxia, is partially dependent on the SDF-1/CXCR4 and CSF-1/CSFR signaling pathways, and promotes polarization toward the M2 phenotype." (PMID 23882218, 2013). "Attempts to target the CD115/CSF-1 pathway in order to inhibit TAMs in mouse tumor models have been reported using various strategies and notably using mAbs." (PMID 24019914, 2013). "Hypoxia-induced HIF-1α stabilization leads to the expression of various angiogenic factors, such as VEGF, and chemotactic factors, such as SDF-1α and CSF-1, by hypoxic tumor cells." (PMID 22888475, 2012). "Further study revealed that the epidermal growth factor (EGF) released by TAMs interacted with the CSF-1 released by tumor cells to promote the migration of the tumor cells." (PMID 22778768, 2012). "Considering the contribution of macrophages and CSF-1 to tumour dissemination and the progression of several inflammatory disorders, this review focuses on our current understanding of macrophage migration and its regulation by CSF-1." (PMID 22505929, 2012). "The release of tumor-released chemokines such as CSF-1 and PIGF attract tumor-associated macrophages (TAM) to the microenvironment, which in turn release multiple factors stimulating invadopodia." (PMID 22481931, 2012).
tumor (continued). "Tumor-associated macrophages secrete epidermal growth factor (EGF) and carcinoma cells secrete CSF-1 to set up a paracrine chemotactic loop that induces comigration of both cell types and promotion of invasion and metastasis." (PMID 22505929, 2012). "In carcinomas monocytes can be recruited by e.g. CCL5 and CSF-1 expressed by tumor cells and this tumor infiltration of monocytes contributes to the tumor-promoting inflammatory response in the cancer." (PMID 22992343, 2012). "Several tumours overproduce colony-stimulating factor-1 (CSF-1) and this has been harnessed to support T cell survival and migration by expression of the CSF-1 receptor in T cells." (PMID 23304553, 2012). "In a mouse model of osteosarcoma, inhibition of Csf1 diminished macrophage recruitment to the tumor environment, suppressed tumor angiogenesis and lymphangiogenesis and reduced tumor metastasis." (PMID 22943568, 2012). "Experimental tumor models suggest that cancer cells release factors such as CSF-1, which stimulates macrophages in the tumor microenvironment, with the subsequent release of EGF, which promotes proliferation of the tumor mass." (PMID 22481931, 2012). "For instance, tumor chemoattractants including colony-stimulating factors (CSF-1), CC chemokines, and VEGF stimulate the recruitment of the infiltrating cells (e.g., monocytes/macrophages) in the lymphatic and blood vessels towards the tumor." (PMID 22481918, 2012). "A study using CSF-1 null mutant PyMT mice showed that macrophage infiltration was a prerequisite for the angiogenic switch which correlates with the transition of the tumour phenotype to malignancy." (PMID 22005011, 2011). "Secondly, the transcription factor Hypoxia Inducible Factor-1 (HIF-1), highly expressed under hypoxic conditions, regulates the attraction of monocytes and macrophages into the tumor amongst others by induction of Colony Stimulating Factor-1 (CSF-1/M-CSF)." (PMID 22176642, 2011). "EGF stimulates the migration of tumour cells and up-regulates the production of CSF-1 which subsequently promotes migration of TAMs." (PMID 22005011, 2011). "Several reports have proposed a chemotactic and paracrine EGF/CSF-1 loop between macrophages and tumour cells, which allows them to work synergistically in an effort to co-migrate." (PMID 22005011, 2011). "In contrast, overexpression of CSF-1 gene resulted in increased macrophage infiltrates and in turn accelerated tumor progression and tumor metastasis." (PMID 21747968, 2011). "Recruitment of macrophages to tumor sites and regulation of their functional specialization through CSF1 promote growth and metastasis in many tumor types, and the development of agents blocking CSF1 signaling has therefore become an active focus of research." (PMID 20981142, 2010). "We then develop an assay for recruitment of host macrophages into the implanted human tumor tissues, allowing us to test the effectiveness of imatinib and of antihuman CSF1 antibodies to block macrophage recruitment in this model system." (PMID 20981142, 2010). "The invasiveness of tumor cells is also stimulated by epidermal growth factor (EGF) synthesized by TAM in response to tumor-derived CSF-1, leading to the induction of several genes involved in the migration of tumor cells." (PMID 20822533, 2010). "Using this model, we demonstrate that an anti-CSF1 monoclonal antibody significantly inhibits host macrophage infiltration into this tumor." (PMID 20981142, 2010). "Recent work has demonstrated that all cases overexpress macrophage colony-stimulating factor (CSF1), usually as a consequence of an activating gene translocation, resulting in an influx of macrophages that form the bulk of the tumor." (PMID 20981142, 2010). "The presence of high levels of CSF1 expression, recruiting a large body of macrophages to the tumor site, appears to be a consistent feature in all forms of this disease." (PMID 20981142, 2010).